IRF7 (interferon regulatory factor 7)
Diseases named in the same sentence as IRF7 in open-access papers (continued):
Sharing a sentence is not in itself a finding about the gene and the disease.
influenza (57 papers, 2011 to 2026). An acute viral infection of the respiratory tract, occurring in isolated cases, in epidemics, or in pandemics; it is caused by serologically different strains of viruses (influenzaviruses) designated A, B, and C, has a 3-day incubation period, and usually lasts for 3 to 10 days. "It has been reported that patients with autosomal recessive (AR) interferon regulatory factor 7 (IRF7) deficiency suffer from life-threatening influenza pneumonia." (PMID 40248710, 2025). "For example, interferon regulatory factor 7 (IRF7)-deficient individuals are healthy, but highly susceptible to life-threatening influenza infections." (PMID 40533538, 2025). "In human IRF7 deficiency, individuals are selectively susceptible to severe infections by influenza and SARS-CoV-2 and show an impaired type I IFN signature." (PMID 36319802, 2023). "An AR deficiency in IRF7, a key transcriptional regulator of type I IFNs, was first reported in a 3-year-old child with critical influenza pneumonia." (PMID 36719370, 2023). "In 2015, we reported autosomal recessive (AR) IRF7 deficiency in an otherwise healthy 7-yr-old girl who had suffered from life-threatening influenza pneumonia at the age of 3 yr." (PMID 36112363, 2022). "Two other patients with IRF7 deficiency suffering from severe influenza pneumonia at the ages of 7 mo and 14 yr have recently been reported." (PMID 36112363, 2022). "In a clinical study, it has been demonstrated that among 22 patients with severe influenza infections, one patient had compound heterozygous mutations in IRF7 and that both of her IRF7 alleles fail to upregulate IFN type I and type III." (PMID 35216030, 2022). "We previously reported inherited IRF7 deficiency in a child with critical influenza pneumonia and two unrelated adults with critical COVID-19 pneumonia." (PMID 34413140, 2021). "IRF7 deficiency can even lead to recurrent influenza infection in humans, emphasizing its crucial role in eliciting proper IFN-I responses." (PMID 33995415, 2021). "Inherited IRF7 deficiency, which underlies critical influenza or COVID-19 pneumonia, disrupts the production of type I IFNs not only by pDCs, but also by all other cell types, including pulmonary epithelial cells." (PMID 34413140, 2021). "Polymorphisms within the TLR7 or IRF7 genes have been associated with disease outcomes in Hepatitis C, Influenza, and HIV." (PMID 31830058, 2019). "The authors described homozygous IRF7 deficiency in a 2.5-year-old girl with severe influenza and acute respiratory distress syndrome." (PMID 30671054, 2018). "In addition, a recently published study revealed an IRF7-dependent amplification of IFNs in an influenza patient carrying a mutation in that gene." (PMID 26329040, 2015). "Similarly, whole-exome sequencing on an otherwise healthy child with influenza-induced life-threatening acute respiratory distress syndrome (ARDS) revealed two compound heterozygous mutations in IRF7, resulting in very little IFN-I production in response to influenza infection." (PMID 36585519, 2023). "We tested the specific hypothesis that inborn errors of Toll-like receptor 3 (TLR3)– and interferon regulatory factor 7 (IRF7)–dependent type I interferon (IFN) immunity that underlie life-threatening influenza pneumonia also underlie life-threatening COVID-19 pneumonia." (PMID 32972995, 2020). "Compound heterozygous mutations in IRF-7 leads to reduced type I interferon responses in otherwise healthy children, and is associated with the development of severe life threatening consequences of influenza infection such as acute respiratory distress syndrome." (PMID 27434537, 2016). "A homozygous deficiency of IRF7 was reported to cause severe influenza and acute respiratory distress syndrome in a 2.5-year-old girl, which highlights the role of IRF7 in severe influenza." (PMID 38257800, 2024).
influenza (continued). "Rare mutations in the interferon regulatory factor 7 (IRF7) gene, a key regulator of antiviral type I Interferons (IFN-I), have been shown to underlie cases of severe influenza COVID-19 pneumonia." (PMID 36585519, 2023). "Patients with AR IRF7 deficiency, AR IRF9 deficiency, and AR or AD TLR3 deficiency were prone to severe influenza." (PMID 36719370, 2023). "AR IRF9 deficiency, AR IRF7 deficiency, AD TLR3, and AR IFNAR2 deficiency also underlie influenza pneumonia." (PMID 36976641, 2023). "The evaluation of influenza viral titers by RT-qPCR and hemagglutination assay (HA) revealed IRF7−/ − MDCK cells had higher viral titers in cell supernatant, including A/pH1N1 (4 to 5-fold) and B/Yamagata (2-fold)." (PMID 36164603, 2022). "The result showed that the MDCK cell knocked down by IRF7 shRNA leads to enhanced influenza propagation." (PMID 36164603, 2022). "The yields of influenza A/pH1N1 (5-fold increased; p = 4.81e−06) observed in IRF7−/− MDCK indicated significantly higher viral titers when compared to WT MDCK cells supernatant." (PMID 36164603, 2022). "The important role of the positive feedback loop generated by IFN and IRF7 was also observed in mice, as influenza-infected IRF7 knockout mice had greater morbidity and mortality and significantly reduced IFN response when compared to wild-type mice." (PMID 34696520, 2021). "The mechanistic role of host expressed genes in influenza has been investigated using knockdown experiments including genes such as IRF7, LAMP3, and DPF2 which in our study were differentially expressed in either influenza, vaccine or both." (PMID 31787983, 2019). "Genes such as Irf7, Irf9, Mx1, Ifit3, Oas1a (L5) were induced most highly in lungs of virally infected mice (influenza and RSV)." (PMID 31253760, 2019). "These diseases encompass herpes simplex encephalitis (HSE) and severe influenza in IRF3- and IRF7/IRF9 deficiency, respectively." (PMID 30671054, 2018). "The most striking example is at the IRF7 locus, where a splice-site SNP affects IRF7 splicing in response to influenza and interferon but only affects the expression of downstream genes in response to flu." (PMID 30446528, 2018). "Strikingly, compound heterozygous null mutations of IRF7, encoding interferon regulatory factor 7 which is triggered by MDA5, have been shown to underlie severe influenza in an otherwise healthy child." (PMID 29018476, 2017). "One research group demonstrated that CS resulted in reduced influenza-mediated induction of IRF7 in upper respiratory tract nasal epithelial cells (NECs)." (PMID 27604339, 2016). "Influenza induction of IRF7 mRNA expression was significantly reduced by 64 % in smokers comparing to nonsmokers." (PMID 27604339, 2016). "Our studies confirm the potential role of Irf7 in influenza pathogenesis in an in vivo model system as suggested by previous in vitro studies." (PMID 26329040, 2015). "It is noteworthy that Irf7 and Mx2 are upregulated upon whole virion influenza vaccine which showed leukopenia in treated animals, and are downregulated upon whole cell pertussis vaccine which showed leukocytosis in treated animals." (PMID 25909814, 2015). "We generated an Irf7 knock-out line on a C57BL/6J background by backcrossing to test the importance of Irf7 for the host response to influenza infection." (PMID 26329040, 2015). "Here, our results demonstrate that the novel MDCK cells expressing shRNA for IRF7 can produce twice to 8 times more influenza viruses than control cells and they will be useful for larger and more rapid production of influenza vaccines." (PMID 23555825, 2013). "In particular IRF7 was identified as a transcription factor controlling the up-regulation of genes following exposure to Mtb and Fuj/02 influenza, whereas genes controlled by this transcription factor only increased late in infection with Schu S4." (PMID 21789257, 2011).
influenza (continued). "Moreover, the expression of Oas1a/g, Irf7, and Il6, that are involved in the immune response to influenza infection, was elevated in lungs." (PMID 41567998, 2025). "The first breakthrough emerged from a study testing the hypothesis that candidate inborn errors of TLR3-, IRF7-, and IRF9-dependent type I IFN immunity previously shown to underlie life-threatening influenza pneumonia might also underlie critical COVID-19." (PMID 37196358, 2023). "Therefore, the monoclonal knock-out (IRF7−/− MDCK) cells based on the CRISPR-Cas strategy would be attractive for further improvement of influenza vaccine production." (PMID 36164603, 2022). "Therefore, the IRF7−/− MDCK cell line was developed based on CRISPR-Cas9 technology to provide higher viral titers for influenza vaccine production." (PMID 36164603, 2022). "IRF7 which is overexpressed due to the influenza infection regulates the antiviral response." (PMID 31665046, 2019). "In addition to IRF7 and IRF9 deficiency predisposing to severe influenza, a RIG-I variant has also been described in an adult patient with severe influenza." (PMID 30671054, 2018). "The importance of Irf7 in influenza pathogenesis was also shown in several in vitro studies." (PMID 26329040, 2015). "Interestingly, we identified Irf7 and Mx2 (Grade 1) as biomarkers not only for influenza vaccine, but also for pertussis vaccine." (PMID 25909814, 2015). "Therefore, the IRF7−/ − MDCK cells could be applied to cell-based influenza vaccine production with higher capacity and efficiency." (PMID 36164603, 2022). "Loss-of-function mutations in Toll-like receptor 3 (TLR3) and interferon regulatory factor 7 (IRF7), which are also important in influenza infections, can lead to increased vulnerability to SARS-CoV-2 infections and might explain severe cases in young and otherwise healthy individuals." (PMID 33804918, 2021). "The significant role of IRF7 in the regulation of the host anti-viral response was further elucidated in humans, in which the IRF7-deficient patient had impaired type I and III IFN responses against primary infection and experienced a life-threatening influenza infection." (PMID 32252379, 2020). "We first tested the specific hypothesis that inborn errors of Toll-like receptor 3 (TLR3)– and interferon regulatory factor 7 (IRF7)–dependent type I interferon (IFN) immunity, which underlie life-threatening influenza pneumonia, may also underlie life-threatening COVID-19 pneumonia." (PMID 32972995, 2020). "Network analysis revealed upregulation of IRF7 in chickens challenged with H5N1 HPAIV, underscoring its involvement in pivotal pathways related to influenza outbreaks and the host’s immune response." (PMID 41042757, 2025). "In conclusion, the IRF7−/− MDCK cells provided higher viral titers of influenza viruses which would be attractive for greater capacity and efficiency of influenza vaccine production." (PMID 36164603, 2022). "We previously tested the hypothesis that critical influenza and critical COVID-19 can be allelic, and showed that life-threatening COVID-19 pneumonia can be caused by rare inborn errors of autosomal genes controlling TLR3- and IRF7-dependent type I interferon (IFN) immunity." (PMID 34413140, 2021). "IRF7 and LAMP3 are members of our influenza and vaccination biologically significant gene lists, while DPF2 was statistically significant with respect to disease state." (PMID 31787983, 2019). "Visualizing these DEGs at 24 hpi, using the “Role of Hypercytokinemia and Hyperchemokinemia in the Pathogenesis of Influenza” pathway, predicts that robust antiviral gene modulation could be through IRF3/IRF7 and other mediators of ISGF3." (PMID 38932231, 2024). "In such a situation, ISGs such as IRF7, MX1 and ISG15 are unable to elicit antiviral effects against some severe influenza strains resistant to these genes, while IFTIM can elicit antiviral effects and circumvent fatal events associated with severe influenza pandemic viruses." (PMID 38932312, 2024).
influenza (continued). "Rsad2, Cxcl10, Saa3, Irf7, and Il1rn, which have been reported in influenza, whereas the role of LCN2 in influenza was still unknown." (PMID 35495713, 2022). "The results suggested that, as we found in human bronchial BCi-NS1.1 cells, IRF7 knockdown inhibited influenza-initiated, but not IFN-β-induced, RIG-I induction in human alveolar AEC II cells." (PMID 32235406, 2020). "We also show that between the two transcription factors IRF3 and IRF7 implied in IFN induction, IRF3 is of less importance than IRF7, but complete abolition of influenza-triggered IFN expression is seen only in the absence of both molecules." (PMID 24278020, 2013). "Thus, influenza infection of airway epithelia induces, via a RIG-I/MAVS/IRF7 dependent pathway, both type I and III IFNs which drive two overlapping and redundant amplification loops to upregulate antiviral genes." (PMID 24278020, 2013). "Here, employing a multi-omics strategy encompassing in vitro assays, in vivo influenza A virus (IAV) infection models, NanoString, transcriptomic analyses, and scGPT-based computational modeling, we dissect the divergent and context-dependent roles of irf3 and irf7." (PMID 41694598, 2026). "While the antiviral protective mechanism of IRF7 in the immune response is well defined, there is evidence suggesting that MX1 may exert its anti-influenza protective effect by downregulating factors such as IL-6, IL-1β and TNFα, among others, involved in excessive cytokine response." (PMID 38932312, 2024). "These cases revealed the indispensable role of human intrinsic (TLR3, IRF7, IRF9, STAT1, and STAT2 in RECs, in which the virus replicates) and innate (IRF7 in plasmacytoid dendritic cells, in which the virus does not replicate) type I and III IFN immunity in host defense against influenza." (PMID 36112363, 2022).
breast cancer (45 papers, 2012 to 2025). A primary or metastatic malignant neoplasm involving the breast. "We include two additional examples where unproductive splicing likely explains the impact of a hyperthyroid-associated locus and a breast cancer-associated locus on the expression levels of IRF7 and PIDD3, respectively." (PMID 40291686, 2025). "Reintroduction of IRF7 to IRF7-deficient tumor cells or supplementation with IFN-α effectively inhibits bone metastasis in a mouse model of breast cancer." (PMID 38512518, 2024). "Higher expression of interferon regulatory factor-7 (IRF7) gene signatures in primary tumours has also been linked to prolonged bone metastasis-free survival in breast cancer." (PMID 33401460, 2021). "In a mouse model of spontaneous bone metastasis, the restoration of interferon regulatory factor 7 (Irf7) suppresses bone metastases through interferon signaling, whereas the deficiency of T and NK cell responses accelerates breast cancer bone metastases." (PMID 32850317, 2020). "Silencing of IRF7 pathways in breast cancer cells promotes breast cancer metastasis, and high expression of the IRF7-regulated genes with breast cancer is associated with prolonged survival." (PMID 28957321, 2017). "Otherwise, the downregulation of IRF7 expression promoted polarization of tumor-associated macrophages (TAMs), which produce anti-inflammatory factors to enhance breast cancer development by promoting immune escape, proliferation, and migration of cancer cells." (PMID 37869102, 2023). "Finally, authors showed that defective irf7 signaling pathway in human breast cancers was significantly associated with bone metastases as the first site of dissemination." (PMID 23269924, 2012). "Meanwhile, miR-1587 can downregulate IRF7 expression to promote the polarization of tumor-associated macrophages (TAMs) to M2 type, which produces anti-inflammatory factors to promote immune escape, proliferation and migration of breast cancer cells, and thus enhancing breast cancer development." (PMID 37251373, 2023). "IRF7 promoted the polarization of tumor-associated macrophages (TAMs) to M2 type, inhibited anti-inflammatory factor production, enhanced immune escape of tumor cells, proliferation and migration of breast cancer cells, and thus promoting the development of breast cancer." (PMID 37251373, 2023). "In breast cancer cells treated with low-concentration Teniposide, both IRF7 and NMI were significantly upregulated at the transcript and protein level." (PMID 38719798, 2024). "For instance, human breast cancer bone metastasis often occurs in conjunction with the presence of IFN-I-deficient cancer cells, attributed to reduced levels of IRF7 expression." (PMID 38512518, 2024). "A further study showed that miR-762 can directly target the 3′ UTR of IRF7 mRNA and inhibit IRF7 expression and in turn promotes the proliferation and invasion of breast cancer cells." (PMID 37251373, 2023). "Because this circRNA is downregulated in MB, if the same mechanism applies, miR-762 would be overexpressed and its target gene IRF7 would be inhibited, as in a study published on breast cancer." (PMID 37835380, 2023). "The clinical correlation pathological study of RACGAP1, IRF7, and DMD showed that RACGAP1 was highly expressed in the high-risk group, indicating that RACGAP1 has a greater impact on patients with breast cancer infected with SARS-CoV-2." (PMID 36060002, 2022). "We quantified phosphorylated and therefore transcriptionally active IRF3 and IRF7 in mammary carcinoma cells using western blots." (PMID 35737804, 2022). "In fact, silencing IRF7 in breast cancer cell lines enhances growth and restoring IRF7 expression reduces metastasis; similarly, in prostate cancer in mice, overexpression of IRF7 significantly reduces metastasis." (PMID 33809496, 2021).